XIAP (X-linked inhibitor of apoptosis)
Diseases named in the same sentence as XIAP in open-access papers (continued):
Sharing a sentence is not in itself a finding about the gene and the disease.
neuroblastoma (continued). "In contrast, ARTS mimetics are a newly-described class of molecules that specifically target XIAP, but there have been limited studies on the effectiveness of targeting XIAP in neuroblastoma." (PMID 37874199, 2023). "To investigate, we screened N-Myc and XIAP expression across a panel of neuroblastoma, and normal liver (THLE3)-and bone marrow (HS5)-derived cell lines." (PMID 37874199, 2023). "Specifically, the expression of XIAP was higher in MYCN-amplified neuroblastoma cells compared with non–MYCN-amplified cells (positive correlation with R2 = 0.76)." (PMID 37874199, 2023). "Consistent with previous findings, these results demonstrated that XIAP expression is necessary for survival of neuroblastoma cells." (PMID 37874199, 2023). "More tellingly, SK-N-AS, a non–MYCN-amplified neuroblastoma cell line with corresponding low XIAP expression was also responsive to all three antagonists." (PMID 37874199, 2023). "Second, using an XIAP-overexpressing human neuroblastoma cell line (SH-SY5YXIAP+) allowed us to identify the molecular pathways implied in the transgene effect on neuronal apoptotic death." (PMID 36769152, 2023). "Medulloblastoma cell lines express higher IAP levels than normal astrocytes and brain tissue, while XIAP is overexpressed in neuroblastoma cells compared with healthy adrenal gland tissue." (PMID 35568716, 2022). "X-linked IAP (XIAP), the most prominent and best-analyzed IAP, is increased in different cancers including neuroblastoma contributing to chemotherapy resistance and unfavorable outcome." (PMID 27655666, 2016). "We have demonstrated cIAP-1 degradation and constant XIAP expression in neuroblastoma cells following treatment with SM LBW242." (PMID 27655666, 2016). "Tumors harvested from neuroblastoma PDXs after exposure to 10 mg/kg A4 at serial timepoints over 48 hours showed an eventual reduction of XIAP tissue expression and increased apoptosis indicated by PARP and caspase-3 cleavage, consistent with in vitro findings." (PMID 37874199, 2023). "This was supported by examining a tissue microarray of neuroblastoma patient samples where 64.3% of patients with MYCN amplification expressed moderate (2+) to high (3+) XIAP whereas the majority of non–MYCN-amplified patients had null to low (1+) XIAP expression." (PMID 37874199, 2023). "Furthermore, our study provides the first proof-of-concept on the efficacy of XIAP-specific antagonist against neuroblastoma tumors in vivo, having determined the murine pharmacokinetic profile of A4 and demonstrated its utility in PDX models." (PMID 37874199, 2023). "Because XIAP reduction is necessary to make sympathetic neuronal progenitors vulnerable to developmental apoptosis, we investigated how removal of high endogenous XIAP expression would impact apoptosis in neuroblastoma cells." (PMID 37874199, 2023). "Furthermore, we previously showed that loss of XIAP-intrinsic antagonist, XAF1, results in failure of caspase-mediated cell death in neuroblastoma, and is associated with poorer survival and disease outcomes." (PMID 37874199, 2023). "We also demonstrated that XIAP degradation, rather than inhibition, is a promising novel treatment approach for high-risk neuroblastoma." (PMID 37874199, 2023). "Engagement and degradation of XIAP by ARTS mimetics is a novel targeting strategy for neuroblastoma that may be especially effective against MYCN-amplified disease with intrinsically high XIAP expression." (PMID 37874199, 2023). "The dependence of neuroblastoma cells on XIAP, render them more sensitive to XIAP-targeting." (PMID 37874199, 2023). "This suggests that BV6 is able to reduce XIAP expression but with less potency than A4 and B3, and may explain why certain neuroblastoma cell lines remain sensitive to BV6 while lines with high XIAP and MYCN expression only respond to A4 and B3." (PMID 37874199, 2023).
neuroblastoma (continued). "Hence, tumor-initiating cells of prenatal embryonal cancers including neuroblastoma which fail to undergo developmental apoptosis are often found to have high XIAP expression, suggesting a dependency on XIAP for survival." (PMID 37874199, 2023). "Intriguingly, NLF, a low XIAP-expressing, MYCN-amplified neuroblastoma cell line, was responsive to all three antagonists which could be mitigated by XIAP overexpression." (PMID 37874199, 2023). "Additionally, cIAP1 and XIAP expression levels increase between primary and recurrent neuroblastoma in vitro, confirming their roles in aggressive recurrent disease." (PMID 35568716, 2022). "Therefore we determined the abundance of cIAP-1 and XIAP protein in neuroblastoma cell lines (n = 6) using Western blot analysis." (PMID 27655666, 2016). "Our findings provide support that XAF1 and its functions such as XIAP inhibition may be a promising pathway to target for neuroblastoma treatment and management." (PMID 27097110, 2016). "We further explored the expression of XIAP in neuroblastoma cell lines." (PMID 19550420, 2009). "Treatment of the neuroblastoma cells with gold(III) porphyrin 1a inhibited the expression of XIAP." (PMID 19550420, 2009). "We hypothesized that MYCN-amplified neuroblastomas would have concomitant high XIAP expression." (PMID 37874199, 2023). "Reduced levels of XIAP, rather than other IAPs, is necessary for developmental apoptosis to proceed, and its upregulation has been found to be associated with chemotherapy resistance and unfavorable outcome in relapsed and advanced stage neuroblastoma." (PMID 37874199, 2023). "Because apoptosis-related protein in the TGFβ signaling pathway (ARTS) is the only XIAP antagonist that directly binds and degrades XIAP, we evaluated the preclinical effectiveness and tolerability of XIAP antagonism as a novel targeting strategy for neuroblastoma." (PMID 37874199, 2023). "Therefore, we surmise that neuroblastoma, particularly high-risk tumors, are addicted to and depend on XIAP for survival, and that targeting XIAP rather than other IAPs can yield specific and effective apoptotic cell death." (PMID 37874199, 2023). "In contrast, we found that pan-IAP antagonists tested in this study including LCL-161, CUDC-427, Debio1143, and BV6 targeted mainly c-IAPs, induced high toxicity in normal cells and were ineffective toward XIAP-dependent, MYCN-amplified neuroblastomas." (PMID 37874199, 2023). "Lastly, HDAC inhibitors including NaB, SAHA and TSA have been shown to increase the sensitivity of neuroblastoma cells to TRAIL-induced death, through downregulation of XIAP and Survivin." (PMID 35568716, 2022). "Treatment of neuroblastoma cell lines with VCR and LCL161 again showed degradation of cIAP-1 by LCL161, as expected XIAP protein levels were only marginally influenced." (PMID 29152118, 2017). "We found that in both SCLC and neuroblastoma, cell lines with higher NE scores were more resistant to drugs that target MEK, mTOR, XIAP, LCK, HSP90, and Abl but were more sensitive to BCL inhibitors, which inhibit anti-apoptotic B-cell lymphoma-2 (Bcl-2) family of proteins." (PMID 37255415, 2023). "Despite the key role played by XIAP in neural crest development, the translational potential of exploiting XIAP antagonism as a treatment strategy for neuroblastoma has not been investigated." (PMID 37874199, 2023). "XIAP-specific antagonists A4 and B3 were the least toxic to noncancerous cells and were the most discriminatory in killing neuroblastoma cells." (PMID 37874199, 2023). "XIAP, the most potent mammalian inhibitor of apoptosis protein (IAP), critically restricts developmental culling of sympathetic neuronal progenitors, and is correspondingly overexpressed in most MYCN-amplified neuroblastoma tumors." (PMID 37874199, 2023). "This suggested that targeting of XIAP, and not c-IAP1, is required for the killing of high-risk neuroblastoma." (PMID 37874199, 2023).
neuroblastoma (continued). "We found that antagonism of XIAP, but not other IAPs, triggered apoptotic death in neuroblastoma cells." (PMID 37874199, 2023). "SMAC mimetics with pan-IAP targeting activity have been widely studied and tested in many cancers while XIAP-specific targeting is a new treatment strategy not previously explored in neuroblastoma." (PMID 37874199, 2023). "In general, the majority of neuroblastoma cell lines expressed higher XIAP protein levels compared with noncancerous normal tissue-derived cell lines." (PMID 37874199, 2023). "Taken together, our findings demonstrated that the loss of XIAP expression mediated by XIAP-specific antagonists A4 and B3—not pan-IAP antagonist BV6—is highly selective and is necessary and sufficient to induce apoptosis in high-risk neuroblastoma cells." (PMID 37874199, 2023). "XIAP degradation is sufficient to kill MYCN-amplified neuroblastoma which overexpresses and relies on XIAP as a brake against cell death, without affecting normal cells." (PMID 37874199, 2023). "Induction of apoptosis by SM is proposed to be mediated by XIAP inactivation and cIAP-1 depletion, consequently we could demonstrate rapid degradation of cIAP-1 by LCL161 in neuroblastoma." (PMID 29152118, 2017). "Furthermore, knock-down or overexpression of XIAP and/or cIAP-1 in combination with VCR would give supplementary evidence on the relevance of XIAP and cIAP expression and the IAP-directed effects of LCL161 in neuroblastoma." (PMID 29152118, 2017). "For childhood neuroblastoma, no clear clinical data is available about XIAP expression and clinical outcome, although XIAP-inhibitors significantly affect tumor growth and death resistance of neuroblastoma in vitro and in vivo." (PMID 25120954, 2014). "Mcl-1 was upregulated after bortezomib exposure in all neuroblastoma cell lines whereas no change was identified in Bcl2, XIAP, survivin and Bcl-xl expression after bortezomib treatment." (PMID 18534018, 2008).
Sepsis (15 papers, 2019 to 2025). Sepsis is defined as life-threatening organ dysfunction caused by a dysregulated host response to infection. "lncRNA SNHG1 shows a protective effect on cardomyocyes in sepsis by targeting miR-181a-5p/X-linked inhibitor of apoptosis (XIAP) axis." (PMID 40041174, 2025). "A recent study by Sun and coworkers revealed that the opposite strand/antisense transcript 1 (KCNQ1OT1) lncRNA inhibits sepsis-induced myocardial injury by regulating the miR192-5p/X-linked inhibitor of apoptosis (XIAP) axis." (PMID 33708127, 2021). "One patient with XIAP deficiency died from sepsis during the donor investigation for HSCT." (PMID 40426715, 2025). "Managing patients with XIAP deficiency is particularly challenging when they present with ambiguous signs, such as worsening pancytopenia, which may be due to HLH secondary to XIAP deficiency or a phenotype secondary to sepsis." (PMID 38912075, 2024). "Consequently, miR-208a-5p inhibits the expression of the X-linked inhibitor of apoptosis protein (XIAP), which is an important caspase inhibitor in the process of apoptosis, leading to myocardial apoptosis and further promoting sepsis-induced cardiac dysfunction." (PMID 39062521, 2024). "In addition, researchers confirmed that KCNQ1 opposite strand/antisense transcript 1 might have cardioprotective impact on sepsis, through interacting with miR-192-5p/X-linked inhibitor of apoptosis protein (XIAP) axis." (PMID 34630395, 2021). "Down-regulation of KCNQ1OT1 advances cardiac injury through regulating miR-192-5p/XIAP axis during sepsis." (PMID 40041174, 2025). "In vitro study, small nucleolar RNA host gene (SNHG) 1 was discovered to protect body against sepsis-induced myocardial injury through the modulation of miR-181a-5p/XIAP axis." (PMID 34630395, 2021). "For instance, lnc‐KCNQ1OT1 relieves sepsis‐induced myocardial injury by regulating cardiomyocyte proliferation and apoptosis by modulating the miR‐192‐5p/XIAP axis." (PMID 34761437, 2021). "Through its activation of the phosphoinositol-3 kinase pathway and phosphorylation of the X-linked inhibitor of apoptosis protein (XIAP), IGF-1 acts to protect Küpffer cells and counter the potentially lethal effects of sepsis." (PMID 33557137, 2021). "KCNQ1OT1, the lncRNA having putative RNA–RNA interaction with TLR2, was found to attenuate sepsis-induced myocardial injury via regulating miR-192-5p/XIAP axis." (PMID 33224264, 2020). "For instance, in myocardial damage mediated by sepsis, the competitive binding of KCNQ1 opposite strand/antisense transcript 1 (KCNQ1OT1) and miR-192-5p modulates the X-linked inhibitor of apoptosis (XIAP) expression, and KCNQ1OT1 overexpression mitigates myocardial injury stemming from sepsis." (PMID 34592882, 2021). "A potential explanation might be that reduced levels of lnc‐KCNQ1OT1 could exacerbate inflammation by regulating the XIAP axis and promoting multiple organ injury by targeting miRNAs (such as miR‐192‐5p and miR‐146a), while inflammation and multiple organ dysfunction often occur in sepsis." (PMID 34761437, 2021).
X-linked lymphoproliferative syndrome (15 papers, 2011 to 2025). "X-linked Lymphoproliferative Syndromes (XLP), arising from mutations in SH2D1A or XIAP genes, are characterized by fulminant Epstein-Barr virus (EBV) infection." (PMID 40674368, 2025). "Other monogenic diseases that produce HLH are Chédiak-Higashi syndrome (LYST), Griscelli syndrome type 2 (RAB27A), Hermansky-Pudlak syndrome (AP3B1), X-linked lymphoproliferative syndrome (XLP)-1 (SH2D1A), and XLP-2 (XIAP)." (PMID 32076423, 2020).
chronic granulomatous disease (14 papers, 2015 to 2025). Chronic granulomatous disease (CGD) is a rare primary immunodeficiency, mainly affecting phagocytes, which is characterized by an increased susceptibility to severe and recurrent bacterial and fungal infections, along with the development of granulomas. "Other IEIs that are associated with colitis include IPEX syndrome, X-linked inhibitor of apoptosis protein (XIAP) deficiency, Chronic Granulomatous disease, Wiskott-Aldrich syndrome and nuclear factor κB essential modulator (NEMO) deficiency." (PMID 35241125, 2022). "For example, hematopoietic stem cell transplantation (HSCT) for patients with an X-linked inhibitor of apoptosis protein (XIAP) deficiency, FOXP3 deficiency, and chronic granulomatous diseases (CGDs) can improve the prognoses of their IBD." (PMID 33553075, 2020). "Among patients treated in the ICU settings there were patients with a diagnosis of chronic granulomatous disease (n = 1), trisomy 21 (n = 1), Wiskott-Aldrich syndrome (n = 1), nuclear factor κB mutation (NFKB2) (n = 1) and X-linked inhibitor of apoptosis protein (XIAP) deficiency (n = 1)." (PMID 34768630, 2021). "Other monogenic conditions include dysfunction of NADPH oxidase complex, X-linked inhibitor of apoptosis (XIAP), lipopolysaccharide responsive beige-like anchor protein (LRBA), cytotoxic T lymphocyte-associated protein 4 (CTLA-4), STAT3, and chronic granulomatous disease." (PMID 33643966, 2020).
hemophagocytic lymphohistiocytosis (13 papers, 2020 to 2025). "A deficiency in XIAP, which is linked to X-linked conditions, can lead to hemophagocytic lymphohistiocytosis (HLH), often triggered by Epstein–Barr virus (EBV) infections." (PMID 40649913, 2025). "XIAP plays roles in cell survival, activation, and negative regulation of the NLRP3 inflammasome, in a manner that patients with XIAP loss-of-function variants are at risk for virally triggered hemophagocytic lymphohistiocytosis." (PMID 36510129, 2022). "One such disease, X-linked inhibitor of apoptosis protein (XIAP) deficiency, is characterized by Epstein–Barr virus-related hemophagocytic lymphohistiocytosis (EBV-HLH)." (PMID 33008347, 2020). "Here, we report the case of a young boy with cardiovascular and renal lesions who was diagnosed with EBV-positive hemophagocytic lymphohistiocytosis (EBV-HLH) secondary to an underlying XIAP gene variant [c.116G > C(p.G39A)]." (PMID 33008347, 2020). "In that regard, mutations in a number of immune-regulatory genes have been described in MIS-C, including SOCS1, XIAP, and CYBB as well as HLA class I alleles and rare heterozygous mutations in genes associated with hemophagocytic lymphohistiocytosis." (PMID 36282598, 2023). "Additionally, approximately 50–70% of patients with X-linked lymphoproliferative disease 2 (XLP2), caused by mutations that limit XIAP expression/function, develop hemophagocytic lymphohistiocytosis (HLH) with symptoms that include hyperinflammation and early-onset chronic haemorrhagic colitis." (PMID 33924766, 2021).
B-cell lymphoma (11 papers, 2015 to 2025). "USP9X also can induce deubiquitylation and stabilization of XIAP, resulting in increased resistance toward MTAs in aggressive B‐cell lymphoma." (PMID 36967563, 2023). "USP9X, a mitotic DUB, can bind to the Gly188 on the BIR2 domain of XIAP to stabilize XIAP, thereby increasing resistance to mitotic spindle poisons in primary human aggressive B-cell lymphoma." (PMID 36551253, 2022). "In aggressive B cell lymphoma, USP9X decreased the degradation of X-linked inhibitor of apoptosis protein (XIAP) to confer resistance against spindle poison–containing chemotherapy." (PMID 28446729, 2017). "We find that primary human aggressive B‐cell lymphoma samples exhibit high USP9X expression that correlate with XIAP overexpression." (PMID 27317434, 2016). "Overexpression of USP9X and XIAP is identified as a predictive biomarker for chemotherapy resistance in aggressive B‐cell lymphoma." (PMID 27317434, 2016). "Accordingly, aggressive B‐cell lymphoma lines with USP9X and associated XIAP overexpression exhibit increased chemoresistance, reversed by specific inhibition of either USP9X or XIAP." (PMID 27317434, 2016). "This process appears to be physiologically related to cancer state, since we found elevated levels of autophagy in various human B-cell lymphoma-derived cell lines where XIAP is overexpressed, compared with wild-type B cells." (PMID 25669656, 2015). "Therefore, USP9X and XIAP are potential predictive biomarkers and targets in combined therapeutical approaches in aggressive B cell lymphoma." (PMID 27766120, 2016). "Furthermore, primary human aggressive B cell lymphomas exhibit high USP9X expression, which correlates with XIAP overexpression and high USP9X/XIAP expression is associated with shorter event-free survival in patients treated with spindle poison-containing chemotherapy." (PMID 27766120, 2016). "Finally, aggressive B cell lymphoma cell lines with USP9X and XIAP overexpression exhibit increased chemoresistance, reversed by specific inhibition of either USP9X or XIAP." (PMID 27766120, 2016). "Together, we specify the USP9X–XIAP axis as a regulator of the mitotic cell fate decision and propose that USP9X and XIAP are potential prognostic biomarkers and therapeutic targets in aggressive B‐cell lymphoma." (PMID 27317434, 2016). "Increased expression of XIAP is found in different cancers, including B‐cell lymphomas; however, the functional relevance has not been fully elucidated." (PMID 27317434, 2016).